LINC02915 (long independently transcribed non-coding RNA 2915)
Synonyms: C15orf54; FLJ39531
Gene: Long non-coding RNA gene on chromosome 15 (39,250,681 to 39,254,845, forward strand). Ensembl gene ENSG00000175746.
Diseases named in the same sentence as LINC02915 in open-access papers:
LINC02915 is named in the same sentence as 8 diseases in open-access papers, as found by Europe PMC text mining. Sharing a sentence is not in itself a finding about the gene and the disease. The quoted sentences say what the papers report.
COVID-19 (1 paper, 2025). A disease caused by infection with severe acute respiratory syndrome coronavirus 2. "Five genes, including PAFAH2, LINC02915, CLSPN, EIF4G1 and IFI27, were predictors of both COVID-19 and RSV-LRTI hospitalization." (PMID 41279033, 2025).
Spastic paraplegia (1 paper, 2024). Complete loss of the ability to move the lower limbs accompanied by spasticity of the lower limbs. "LINC02915 is noncoding and located in an intron, but it has been associated with spastic paraplegia." (PMID 39062924, 2024).
LINC02915 also shares sentences with these, for which no sentence is quoted: gastric cancer (2 papers); breast carcinoma (1); heart failure (1); neurological diseases (1); Sepsis (1); tumour (1).